ZFYVE1 (zinc finger FYVE-type containing 1)
Description:
Plays a role in the formation of lipid droplets (LDs) which are storage organelles at the center of lipid and energy homeostasis. Regulates the morphology, size and distribution of LDs. Mediates the formation of endoplasmic reticulum-lipid droplets (ER-LD) contacts by forming a complex with RAB18 and ZW10. Binds to phosphatidylinositol 3-phosphate (PtdIns3P) through FYVE-type zinc finger. (Microbial infection) Upon SARS coronavirus-2/SARS-CoV-2 infection, mediates through binding with non-structural protein 6 (nsp6) the replication organelle-lipid droplet association required to sustain viral replication.
Synonyms: DFCP1; KIAA1589; TAFF1; ZNFN2A1; PPP1R172; SR3
Tractability: PROTAC: ubiquitination databases record sites on it; its protein half-life has been measured.
Gene: Protein-coding gene on chromosome 14 (72,969,451 to 73,027,131, reverse strand). Ensembl gene ENSG00000165861.
Subcellular location: Golgi apparatus, Golgi stack; Golgi apparatus; Endoplasmic reticulum; Lipid droplet; Preautophagosomal structure; Mitochondrion
Subcellular location (Human Protein Atlas): Endoplasmic reticulum
Gene Ontology:
Molecular function: 1-phosphatidylinositol binding; phosphatidylinositol-3,4,5-trisphosphate binding; phosphatidylinositol-3,4-bisphosphate binding; phosphatidylinositol-3-phosphate binding; protein binding; zinc ion binding; metal ion binding
Biological process: cellular response to starvation; host-mediated activation of viral genome replication; lipid droplet formation; macroautophagy
Cellular component: autophagosome; endoplasmic reticulum; endoplasmic reticulum membrane; extrinsic component of omegasome membrane; Golgi apparatus; Golgi stack; lipid droplet; membrane; mitochondria-associated endoplasmic reticulum membrane contact site; mitochondrion; omegasome; perinuclear region of cytoplasm; phagophore assembly site
Genetic constraint (gnomAD): Loss-of-function variants: 30 observed, 75.65 expected, observed/expected ratio (o/e) 0.4, 90% interval 0.3 to 0.54. The upper end of that interval is the gene's LOEUF score, 0.54, which puts it in group 2 of 6, group 1 being the genes least tolerant of losing a copy. Missense variants: 695 observed, 1,042.2 expected, observed/expected ratio (o/e) 0.67, 90% interval 0.63 to 0.71. Synonymous variants: 335 observed, 399.45 expected, observed/expected ratio (o/e) 0.84, 90% interval 0.77 to 0.92.
Homologues: Orthologues: chimpanzee ZFYVE1 (99% identical), macaque ZFYVE1 (99% identical), mouse Zfyve1 (97% identical), dog ZFYVE1 (97% identical), rat Zfyve1 (96% identical), pig ZFYVE1 (96% identical), rabbit ZFYVE1 (95% identical), guinea pig ZFYVE1 (95% identical), tropical clawed frog zfyve1 (81% identical), zebrafish zfyve1 (77% identical), Drosophila melanogaster CG31064 (9% identical), Caenorhabditis elegans lst-2 (9% identical), and 1 more. Paralogues in human: ZFYVE26 (16% identical), ZFYVE28 (13% identical), RUFY1 (12% identical), RUFY3 (12% identical), RUFY2 (11% identical), PLEKHM2 (10% identical), SNX29 (9% identical), ZFYVE16 (7% identical), RUNDC3A (7% identical), PLEKHF1 (6% identical), PLEKHF2 (6% identical), ZFYVE19 (6% identical), and 1 more.
Diseases named in the same sentence as ZFYVE1 in open-access papers:
ZFYVE1 is named in the same sentence as 10 diseases in open-access papers, as found by Europe PMC text mining. Sharing a sentence is not in itself a finding about the gene and the disease. The quoted sentences say what the papers report.
melanoma (1 paper, 2021). A malignant, usually aggressive tumor composed of atypical, neoplastic melanocytes. "The findings showed that ZNF775, GBA, ALKBH5, ZFYVE1, and MIEF2 were significantly upregulated in Treg cells of metastatic melanoma compared with primary melanoma." (PMID 34159752, 2021).
viral infection (1 paper, 2020). "Coimmunoprecipitation experiments indicated that ZFYVE1 was constitutively associated with MDA5 before and after viral infection." (PMID 32251420, 2020). "Following viral infection, we immunoprecipitated ZFYVE1, MDA5 or RIG-I, and the protein-bound viral RNA was detected by qPCR with primers targeting various regions of the viral genome." (PMID 32251420, 2020). "The simplest explanation for our data is that upon viral infection ZFYVE1 competes with MDA5 for viral RNA binding." (PMID 32251420, 2020). "In addition, viral infection induced oligomerization of ZFYVE1, while ZFYVE1 had an inhibitory role on virus-induced oligomerization of MDA5." (PMID 32251420, 2020).
cancer (3 papers, 2009 to 2023). A tumor composed of atypical neoplastic, often pleomorphic cells that invade other tissues. "The possible association existing between ZNF83, TNPO2, ZFYVE1 and cancer was discussed in the present study for the first time." (PMID 19171046, 2009).
infection (1 paper, 2020). The state of being infected such as from the introduction of a foreign agent such as serum, vaccine, antigenic substance or organism. "The serum cytokine levels induced by infection of EMCV were elevated in Zfyve1-/- in comparison to wide-type mice, and ZFYVE1-deficient mice were less susceptible to EMCV- but not VSV-induced death." (PMID 32251420, 2020). "In similar experiments, VSV genomic copies and viral titers in the lungs of Zfyve1-/- mice after infection were comparable to those of Zfyve1+/+ mice." (PMID 32251420, 2020). "Consistently, EMCV genomic copies and viral titers in the brain of Zfyve1-/- mice after infection were significantly decreased compared to those of Zfyve1+/+ mice." (PMID 32251420, 2020). "In addition, EMCV infection increased the oligomerization of ZFYVE1, and the oligomerization of endogenous MDA5 induced by transfected poly(I:C)-HMW was increased in Zfyve1-/- in comparison to Zfyve1+/+ MLFs." (PMID 32251420, 2020).
ZFYVE1 also shares sentences with these, for which no sentence is quoted: osteosarcoma (2 papers); hepatocellular carcinoma (1); metastatic melanoma (1); renal cell carcinoma (1); spina bifida (1); tumor (1).